MYO3B (myosin IIIB)
Description:
Probable actin-based motor with a protein kinase activity. Required for normal cochlear hair bundle development and hearing. Plays an important role in the early steps of cochlear hair bundle morphogenesis. Influences the number and lengths of stereocilia to be produced and limits the growth of microvilli within the forming auditory hair bundles thereby contributing to the architecture of the hair bundle, including its staircase pattern. Involved in the elongation of actin in stereocilia tips by transporting the actin regulatory factor ESPN to the plus ends of actin filaments.
Tractability: Small molecule: a high-quality ligand is known; it belongs to a druggable protein family. PROTAC: ubiquitination databases record sites on it; a small molecule that binds it is known.
Target class: STE protein kinase group; STE protein kinase STE20 family; Enzyme; Kinase; Protein Kinase; STE protein kinase NinaC subfamily
Gene: Protein-coding gene on chromosome 2 (170,178,145 to 170,655,171, forward strand). Ensembl gene ENSG00000071909.
Subcellular location: Cytoplasm, cytoskeleton; Cell projection, stereocilium
Pathways (Reactome):
Sensory Perception: Sensory processing of sound by inner hair cells of the cochlea; Sensory processing of sound by outer hair cells of the cochlea
Gene Ontology:
Molecular function: protein binding; microfilament motor activity; protein serine/threonine kinase activity; ATP binding; cytoskeletal motor activity; protein kinase activity; protein serine kinase activity
Biological process: cochlea morphogenesis; positive regulation of filopodium assembly; regulation of actin filament length; sensory perception of sound; auditory receptor cell stereocilium organization
Cellular component: filopodium tip; photoreceptor inner segment; stereocilium tip; cytoplasm; cytoskeleton; myosin complex; photoreceptor outer segment; stereocilium
Genetic constraint (gnomAD): Loss-of-function variants: 112 observed, 130.34 expected, observed/expected ratio (o/e) 0.86, 90% interval 0.74 to 1. The upper end of that interval is the gene's LOEUF score, 1, which puts it in group 4 of 6, group 1 being the genes least tolerant of losing a copy. Missense variants: 1,338 observed, 1,406.8 expected, observed/expected ratio (o/e) 0.95, 90% interval 0.91 to 1. Synonymous variants: 466 observed, 499.32 expected, observed/expected ratio (o/e) 0.93, 90% interval 0.86 to 1.01.
Homologues: Orthologues: chimpanzee MYO3B (99% identical), macaque MYO3B (97% identical), dog MYO3B (91% identical), rabbit MYO3B (90% identical), mouse Myo3b (85% identical), rat Myo3b (85% identical), guinea pig MYO3B (84% identical), pig MYO3B (84% identical), tropical clawed frog myo3b (76% identical), zebrafish myo3b (69% identical). Paralogues in human: MYO3A (57% identical), MYO16 (28% identical), MYO15A (26% identical), MYO7A (25% identical), MYO7B (25% identical), MYO10 (24% identical), MYO9A (24% identical), MYO9B (23% identical), MYO5A (22% identical), MYH2 (21% identical), MYH3 (21% identical), MYH6 (21% identical), and 32 more.
Diseases named in the same sentence as MYO3B in open-access papers:
MYO3B is named in the same sentence as 15 diseases in open-access papers, as found by Europe PMC text mining. Sharing a sentence is not in itself a finding about the gene and the disease. The quoted sentences say what the papers report.
hearing loss (3 papers, 2016 to 2021). "It is therefore possible that the association of MYO3B, ARID5B and ZNF318 with tinnitus is secondary to their role in hearing since tinnitus is usually manifested when there is a hearing loss present." (PMID 33742053, 2021). "It is also possible that MYO3B could partially compensate for the effects of mutations in MYO3A and the effectiveness of this compensation could vary among individuals, explaining non-penetrance and differences in age of onset of hearing loss." (PMID 29880844, 2018).
Obesity (2 papers, 2018 to 2020). Accumulation of substantial excess body fat. "In addition, previous studies also indicated that MYO3B was associated with obesity and Kawasaki disease." (PMID 30326835, 2018).
breast carcinoma (1 paper, 2024). "SCUBE2, B4GALT1 and MYO3B genes also exemplify the relationship between decitabine-induced gain of multiple ER-bound enhancer–promoter interactions and activation of their ER target genes that are associated with good prognosis in ER+ breast cancer." (PMID 38182927, 2024).
deafness (1 paper, 2024). An inherited or acquired condition characterized by the complete loss of the ability to hear from one or both ears. "Myo3a−/− mice have normal hearing at 1 month of age while a double knockout of Myo3a and Myo3b results in profound deafness and a dysmorphic staircase architecture of hair cell stereocilia bundles." (PMID 38562617, 2024).
intracranial aneurysm (1 paper, 2024). "It was reported that the polymorphisms of UBR3 and MYO3B were related to saccular intracranial aneurysm in Portugal39." (PMID 38370381, 2024).
prostate carcinoma (1 paper, 2015). A carcinoma that arises from epithelial cells of the prostate gland. "Human MYO3B or its orthologues have been associated to such diverse phenotypes as Mycobacterium bovis resistance in cattle and to the development of urinary symptoms after radiotherapy for prostate cancer." (PMID 26186006, 2015).
sarcoma (1 paper, 2024). A usually aggressive malignant neoplasm of the soft tissue or bone. "It should be noted that two patients in our cohort had somatic mutations in MYO3A and MYO3B (patients 17 and 33, respectively), further indicating a role for these genes in sarcoma." (PMID 39037077, 2024).
cancer (2 papers, 2024 to 2025). A tumor composed of atypical neoplastic, often pleomorphic cells that invade other tissues. "In a study reporting germline PVs, among 1120 pediatric cancer patients neither MYO3A, MYO3B, or CHD1L were covered." (PMID 39037077, 2024).
infection (1 paper, 2024). The state of being infected such as from the introduction of a foreign agent such as serum, vaccine, antigenic substance or organism. "Analysis of the expression profiles in our study revealed that miR-449a and miR-449b were highly expressed at the early stage of infection, whereas the expression of their target genes L1CAM, MYO3B, SCIN, and STMN1 decreased." (PMID 38178220, 2024).
MYO3B also shares sentences with these, for which no sentence is quoted: diabetes (1 paper); hyperthyroidism (1); Kawasaki disease (1); male pattern baldness (1); periodontitis (1); Tinnitus (1).